TUBB3 (tubulin beta 3 class III)
Diseases named in the same sentence as TUBB3 in open-access papers (continued):
Sharing a sentence is not in itself a finding about the gene and the disease.
tumor (continued). "In this study, a prospective randomized controlled trial was conducted to measure the molecular markers (mRNA expression of ERCC1, RRM1, and TUBB3) in tumour tissue specimens from patients who needed adjuvant chemotherapy after surgery." (PMID 34603450, 2021). "More cells were arrested in G2/M phase of the cell cycle when TUBB3 levels were reduced, consistent with a known role of TUBB3 in regulating cell cycle progression of tumour cells." (PMID 32909943, 2020). "In multivariate analysis, distant metastasis (p = 0.002), high tumor budding (p = 0.004), and high TUBB3 H-score (p = 0.015) remained independent prognostic factors for inferior PFS." (PMID 33256003, 2020). "In our study, TUBB3 was expressed in tumor cells and the stroma of the invasive front, and upregulation of TUBB3 was observed during Matrigel penetration and was associated with an EMT phenotype." (PMID 33256003, 2020). "ATCs revealed the highest levels of TUBB3, followed by cPTCs, infiltrative FVPTCs, invEFVPTCs and NIFTPs, both in tumor cells and stromal cells, although the differences between ATCs and cPTCs were not statistically significant." (PMID 33256003, 2020). "This was consistent with the findings that high TUBB3 expression and microtubule-associated protein tau (MAPT) inversely correlated with the sensitivity to paclitaxel in cells isolated from fresh tumor tissue." (PMID 32751679, 2020). "In cPTCs and infiltrative FVPTCs, TUBB3 was selectively expressed in the tumor and stromal cells at the invasive margin, forming a band-like structure." (PMID 33256003, 2020). "RPPH1 promotes CRC cells metastasis by binding to TUBB3, thus inhibiting its ubiquitination and enhancing exosomes-mediated macrophages M2 polarization and influences the tumor microenvironment." (PMID 31685807, 2019). "In this study, we found that TUBB3 overexpression induced higher tumor growth in both in vitro and clinical samples." (PMID 30034996, 2018). "It was reported that miR-200c exerted its influence to suppress TUBB3 gene/protein expression, when the HuR staining was found in nucleus, and as a consequence the tumor exhibited a good outcome." (PMID 28881640, 2017). "In contrast, the protein and mRNA expression levels of STMN1 and TUBB3 in the cancer tissues were significant higher than that in the adjacent non-tumor tissues (p≤0.001)." (PMID 29113350, 2017). "IHC was used to detect the protein expression levels of BRAC1, STMN1, MAPT and TUBB3 in cancer tissues and adjacent non-tumor tissues." (PMID 29113350, 2017). "miR-200c can directly target the 3’-UTR of TUBB3 mRNA, resulting in post-transcriptional suppression of TUBB3 expression, thereby improving sensitivity of paclitaxel, vincristine, and other drugs in tumor cells." (PMID 28881640, 2017). "Both tumor types exhibited classic histology, and similar expression patterns for expected Shh-MB neural markers (Atoh1, TUBB3 and GFAP) and Hh target genes (Gli1, Mycn and Ccnd1)." (PMID 27823583, 2016). "The direct silencing of TUBB3 reverses induced multiple cross-resistance, reduces drug-resistant tumor mass, and suppresses the impaired microtubule stability status of PTX-resistant cells with transient cross-resistance." (PMID 27284014, 2016). "To further elaborate the consequences of scant TUBB3 on P-gp expression, we determined their protein expression levels in extracts from frozen xenograft tumor tissue samples." (PMID 27284014, 2016). "In tumors such as tumor 73 with elevated expression of both hGBP-1 and TUBB3 (and it’s a primary tumor so the sample was all tumor) both proteins are expressed in all tumor cells." (PMID 28090373, 2016). "In support of the identified TUBB3-dependent effects in multidrug resistance in vitro, a tumor xenograft model was used to examine the probable drug resistant-tumor physiological alteration in vivo by modifying TUBB3 transcription." (PMID 27284014, 2016).
tumor (continued). "Low expression levels of TUBB3 was a favorable indicator for tumor response to paclitaxel and vinblastine, whereas high levels were associated with drug resistance." (PMID 24649266, 2013). "When the HuR pattern of staining was only nuclear, the prevalent mechanism by which miR-200c exerted its influence was a suppression of TUBB3 gene/protein expression, and as a consequence the tumor exhibited a good outcome." (PMID 23394580, 2013). "Relative to the other AD samples, both AD5 and the AYA group exhibited higher expression of genes associated with aggressive tumor features and inflammation (e.g., CXCL2, TUBB3, RRM2, and MMP1) and lower expression of differentiation markers and metastatic regulators (e.g., KIT and NCAM1)." (PMID 41374320, 2025). "Moreover, certain studies have indicated that high expression of TUBB3 leads to increased drug resistance in tumor cells, which adversely affects patient prognosis." (PMID 38562930, 2024). "In terms of tumor microenvironment signatures, the general marker TUBB3 was positively correlated with gene sets involved in both pro-tumor (e.g., CAF and Macrophage DC traffic,) and anti-tumor (e.g., MCHII, Effector cells, T cells, and checkpoint inhibition) actions." (PMID 36648874, 2023). "Among those ASEs associated with metastasis, alternative splicing of GIT2 and TUBB3 might play key roles in tumor metastasis in KIRC patients." (PMID 37810965, 2023). "Like Vinca alkaloids, Taxol has been reported to alter the level of TUBB3 expression in tumours." (PMID 35573698, 2022). "Additional studies are required to assess whether Snail or Slug can directly bind to the TUBB3 loci and regulate its expression, especially given βIII-tubulin’s roles in drug resistance and tumor aggressiveness." (PMID 35573698, 2022). "Genomic advances such as single cell analysis and spatial transcriptomics may lead to improved identification of differences between cell-types, and the regulation of TUBB3 within the tumour microenvironment." (PMID 35573698, 2022). "It is becoming apparent that mechanisms driving aberrant TUBB3 expression in tumours are complex and may vary depending on cell type and gender." (PMID 35573698, 2022). "We hypothesize that, in TUBB3‐expressing mCRPC, hypoxia and angiogenesis may increase the prosurvival signals that βIII‐tubulin provided for tumor cells, which is beyond the mere scope of microtubule dynamics." (PMID 34318630, 2021). "Moreover, a well-described tumor suppressor miR-200c targets TUBB3, MSN, and ARHGAP19, which regulate multiple cytoskeletal-related events." (PMID 34298609, 2021). "In our study, TUBB3 was expressed not only in the tumor cells but also in the neighboring stroma." (PMID 33256003, 2020). "Our study indicates that TUBB3 plays a role in tumor progression via EMT." (PMID 33256003, 2020). "For TUBB3, the Fisher's exact test was significant in 4 of 40 tumor types." (PMID 31479512, 2020). "This suggests that microenvironmental factors that induce TUBB3 expression in tumor cells might also function in a similar way in stromal cells." (PMID 33256003, 2020). "Tumor budding showed strong TUBB3 expression and was frequent in cPTCs and infiltrative FVPTCs." (PMID 33256003, 2020). "The source of TUBB3 in CAFs might be cancer cells, with paracrine regulation, and these CAFs are believed to participate in angiogenesis, tumor growth, and progression." (PMID 33256003, 2020). "Expression of TUBB3 was diffuse and strong throughout the tumor area in ATCs." (PMID 33256003, 2020). "For TUBB3, the Fisher's exact test was significant in 8 of 40 tumor types." (PMID 31479512, 2020). "PD‐L1 expression was associated with TUBB3 positivity in 8 of 40 tumor types; hence, taxanes and immunotherapy is unlikely to be of benefit." (PMID 31479512, 2020).
tumor (continued). "In U-87MG cell-derived tumours, immunostaining for mature neuronal markers, including tubulin beta 3 (TUBB3) and glutamate decarboxylase 1 (GAD1/GAD-67), involved in GABA synthesis, revealed high expression levels in si-hVDAC1-TTs and low expression in the NT-TTs." (PMID 30544833, 2018). "We also found that the expression of TS, TUBB3, and TOP2A were associated with tumor grade." (PMID 29487694, 2018). "TUBB3 is mainly expressed in neurons and the testes, but there has been a report that some cancers overexpress TUBB3 and it may be involved in tumor aggressiveness and prognosis." (PMID 30034996, 2018). "TUBB3 gene expression was evaluated on RNA isolated from tumor tissue." (PMID 27988838, 2017). "This may suggest that modification of mt stability through TUBB3 affects the distinctive EMT-driven hostile outgrowth of the tumor inter-cellular system in cancers with MDR, at least in vitro." (PMID 27284014, 2016). "Thus, reduced tumor mass in response to TUBB3 knockdown is influenced by Akt and VEGF signals, which we found to suppress Akt gene expression and attenuate VEGF levels in A549-PacR/5-FU tumors." (PMID 27284014, 2016). "Overexpression of TUBB3 has been correlated with tumor resistance to taxane chemotherapy." (PMID 25946136, 2015). "Clinical and tumor data for each patient was compared with the degree of TUBB3 expression." (PMID 24396456, 2014). "Therefore, the association between ERCC1, TYMS, RRM1, TUBB3 and TOP2A expression levels with the pathogenesis and development of ESCC was investigated using a clustered analysis in terms of tumor invasion and lymphatic and distal metastasis." (PMID 24926347, 2014). "When paired teratomas from the same animals were compared, transchromosomic tumours showed a three-fold lower percentage of neuroectodermal tissue, as well as significantly reduced mRNA levels for neuron specific (Tubb3) and glia specific (Gfap) genes, relative to euploid controls." (PMID 18047653, 2007). "Most specimens represented chemotherapy-naive tumour and results might have been confounded by other mechanisms that control TUBB3 expression, such as hypoxia via transcription factors HIF-1α/HIF-2α epigenetic modifications or differences in warm ischaemia time and treatments rendered." (PMID 35149854, 2022). "Since other neuronal differentiation factors mentioned previously are also linked to this altered TUBB3 expression, it poses the question—are dysregulated processes associated with neuronal gene regulation the primary causes of aberrant TUBB3 expression in tumours of non-neuronal origin?" (PMID 35573698, 2022). "TUBB3 expression has been considered a predictor of tumor progression and aggressive behavior regardless of therapeutic options in various tumors; however, other studies reported that high TUBB3 expression was associated with a superior response to drugs." (PMID 33256003, 2020). "Specifically, the expressions of RRM1, ERCC1, and TUBB3 are inversely correlated with tumor responses to anti-metabolites such as gemcitabine, platinum-based agents, and spindle poisons, respectively, which may help explain why these drugs have shown little efficacy in vivo or in clinical studies." (PMID 29487694, 2018). "Consistently, the mRNA and protein levels of TUBB3, STMN1, and TAU were dramatically reduced in the tumour tissues of the RNF31 knockdown and IPO13 knockdown groups treated with PTX." (PMID 39915011, 2025). "In an attempt to characterize the effect of lncRNA ROR and its downstream pathway TESC/ALDH1A1/TUBB3/PTEN axis on PTC in vivo, transduced TPC-1 and BCPAP cells were subcutaneously inoculated into BALB/c nude mice to construct a PTC tumor-bearing model." (PMID 35173149, 2022). "Among the proteins with higher prot_score, ENO1, TUBB3, MYH9 and YBX1 were reported to promote or inhabit tumor progression by interacting with lncRNAs 46-51." (PMID 35541917, 2022).
tumor (continued). "We found a significant reduction of the Tubb3+ TAMs after depletion (DT group), which was successfully rescued in the LLC tumor by the adoptive transfer of BMDMs in vivo." (PMID 36206343, 2022). "PTC tumor and adjacent tissues were obtained, followed by measurement of lncRNA ROR and TESC, ALDH1A1, and TUBB3 expression." (PMID 35173149, 2022). "Together, these findings suggest REST as a transcriptional silencer of TUBB3 and that dysfunctional REST, in conjunction with epigenetic modifications in TUBB3 intron 1, may be important mechanisms underlying aberrant TUBB3 expression in tumours of non-neuronal origin." (PMID 35573698, 2022). "Further analysis indicated that differential methylation of the CpG island in tumours mainly affected the expression of MC1R, and less so of TUBB3." (PMID 33248005, 2021). "Compared with A375 cells, A375 xenograft tumor displayed an upregulation for glial and neuronal genes (GFAP, BDNF, MAP2, MTURN, ROBO2, SYT1 and TUBB3) and neural stemness genes (ASCL1, MSI1, PAX6, PDGFRA, SOX9, VIM, ZIC1/2)." (PMID 33468253, 2021). "VEGFR2 and TUBB3 are the drug action targets of Ramucirumab and TXT, respectively, and STMN1 has been suggested to be a marker of tumor resistance to taxanes." (PMID 32993587, 2020). "While LMS is relatively rare, it has a very poor prognosis; therefore, we decided to analyze the gene expression of TUBB3 and PTGER4 in 54 primary LMS tumor samples from the TCGA representing conventional and poorly differentiated LMS." (PMID 31635323, 2019). "Serial tumor tissue sections were taken, and HAS3, differentiation markers (GFAP and TUBB3), and an autophagic marker (LC3) were detected by IHC." (PMID 31274246, 2019). "Only following long-term treatment with si-hVDAC1 did tumor cells express neuronal markers such as those of astrocytes (i.e., GFAP, TUBB3, and GAD-67), suggesting that CSCs are differentiated into cells resembling astrocytes or neurons." (PMID 31661894, 2019). "Immunohistochemical examination of 10 distinct tumors showed that in most of the tumors, Tomato+ tumor cells express melanocytic markers Dct and MITF, neuronal markers Nestin, Tubb3 and Gfap, mesenchymal marker Pdgfra and proliferation marker Ki67." (PMID 31685822, 2019). "We found that taxane-resistant tumor showed elevated expression levels of TUBB1 and lower expression levels of TUBB3, TUBB4B, and TUBB6 genes when compared with the sensitive tumors." (PMID 30126203, 2018). "We found that tumor tissues express significantly higher levels of TUBB and TUBB3 and significantly lower levels of TUBB2B, TUBB6, and TUBB7P pseudogene." (PMID 30126203, 2018). "This up-regulation expands to other potential tumor markers including A1AT1, tropomyosin-4, TUBB3, ACTN4, DDX3X, LMNB1, PARP and vimentin." (PMID 29109428, 2017). "Tumour-derived cultures are usually similar to neural stem cell cultures in that NES-, GFAP-, OLIG2- and TUBB3-positive cells are all present." (PMID 27991551, 2016). "Our study identifies that the response of TUBB3 from FOXO3a-regulated ABCB1 is a critical feedback mechanism to genetically identify cross-resistance in PTX-resistant cancers and its tumor progression." (PMID 27284014, 2016). "We observed a clear decrease in TUBB3 expression at both the transcriptional and translational levels in let-7b-transfected KRAS mutant tumor cells, paralleling with the decline of mutant KRAS in these cells." (PMID 25946136, 2015). "Knockdown of TUBB3 using siRNA has been shown to significantly increase the cytotoxicity of paclitaxel and induce apoptosis in KRAS mutant tumor cells." (PMID 25946136, 2015). "The immunostaining patterns for TUBB3 were cytoplasmic, whereas the ERCC1 expression patterns in the tumor cells were nuclear The expression status of TUBB3 and ERCC1 did not correlate with each other (P = 0.245)." (PMID 24053422, 2013). "Immunohistochemical staining for TUBB3 and ERCC1 was performed using paraffin wax-embedded tumor tissues." (PMID 24053422, 2013).
tumor (continued). "Furthermore, knockdown of Osgin1 and TUBB3 reversed NSCLC tumor progression, and Osgin1 knockdown additionally restored the effect of the anti-cancer drug Gefitinib in tumor suppression." (PMID 40149945, 2025). "TUBB3 is expressed in non-neuronal tumor cells and plays a key role in regulating cell cycle progression." (PMID 36656905, 2023). "Consequently, our study revealed that lncRNA ROR promotes the cell malignant behaviors and tumor growth of PTC, which is achieved in part by the TESC/ALDH1A1/TUBB3/PTEN axis." (PMID 35173149, 2022). "TUBB3 has also been found in non-neuronal cells such as tumor cells and normal cells such as fibroblast, stroma cells, endocrine cells, and perivascular cells, including smooth muscle, and pericytes." (PMID 36331951, 2022). "This method of quantifying exosomal TUBB3 expression based on mRNA circulating in plasma is more sensitive than circulating tumor cells and has a lower false‐negative rate." (PMID 34318630, 2021). "In 2 of 40 tumor types, TMB‐H and TUBB3 negative were associated; hence, combinations of taxanes and immunotherapy are likely beneficial in this tumor type." (PMID 31479512, 2020). "High TUBB3 expression, along with the presence of tumor budding, was a negative prognostic factor in cPTC." (PMID 33256003, 2020). "Additionally, RT-PCR also indicated the gene expression of iPSC-derived tumor tissue in three germ layers, demonstrating expressions of GATA4 in endoderm; HAND1 and GATA6 in mesoderm; and TUBB3, MAP2, and GFAP in ectoderm." (PMID 33224204, 2020). "Analyzing expression profile of BC tumors and tumor-adjacent normal breast tissues showed upregulation of TUBA1A, TUBA1C, TUBB and TUBB3 and downregulation of TUBB2A, TUBB2B, TUBB6, TUBB7P pseudogene, and TUBGCP2 in the tumor tissues compared to the normal breast tissues." (PMID 30126203, 2018). "Here, we showed that following metabolism reprogramming, the residual “tumour” derived from the U-87MG cancer cell line that originated from astroglia showed up-regulated expression of neuronal markers, such as GFAP, TUBB3 and GAD-67, an enzyme involved in GABA synthesis." (PMID 30544833, 2018). "For patients with advanced tumor infiltration the kind of therapy – primary surgery vs neoadjuvant therapy, or chemoradiation vs. chemotherapy had no influence on the TUBB3 expression." (PMID 29383151, 2017). "The present study demonstrates that TUBB3 transcription can be controlled by FOXO3a-mediated ABCB1 regulation and can subsequently promote the profusion of multiple cross-resistance and govern the tumor progression of PTX-resistant cancers." (PMID 27284014, 2016). "Recent data consistently suggest that TUBB3 and TS expression were significantly correlated to poor outcomes in NSCLC patients; therefore, their expression could correlate to aggressive tumour behavior and increased proliferative activity." (PMID 26663950, 2015). "Notably, TUBB3 is a direct target of miRNA-200c, which is an important tumor suppressor that induces epithelial differentiation and reverts EMT in tumor cells." (PMID 25946136, 2015). "In contrast, Scratch1 may not be involved with TUBB3 regulation in a cancer setting due to its lack of expression in a wide range of patient samples obtained from different tumours." (PMID 35573698, 2022). "However, the expression level of MAPT and TUBB3, tumor size, tumor location, age, pathological type, clinical stage were not significantly correlated with the survival time of patients." (PMID 29113350, 2017). "Therefore, both hGBP-1 and TUBB3 may be expressed in the same tumor cells but it is not a prerequisite for the recurrent tumors." (PMID 28090373, 2016). "While the residual melanocytes and/or endothelial cells present in each sample were positive for TUBB3, BPDCN tumor cells turned out negative in all instances but one." (PMID 34572907, 2021).